SOX2 (SRY-box transcription factor 2)
Diseases named in the same sentence as SOX2 in open-access papers (continued):
Sharing a sentence is not in itself a finding about the gene and the disease.
cancer (continued). "Both Oct4 and Sox2 are essential for self-renewal of stem cells, normal or cancer cells." (PMID 39071677, 2024). "Investigations into the mechanistic basis of Sox2 regulation, with a focus on the generation of cancer stem cells and chemoresistance, might lead to new therapeutic approaches involving Sox2-targeted treatment." (PMID 38473392, 2024). "Therefore, previous concepts regarding the role of SOX2 in the stemness of various cancers, primarily derived from shRNA- or siRNA-mediated approaches, need to be reconsidered with caution." (PMID 38334608, 2024). "The relationship between SOX2 expression level and immune cancer subtypes was also explored." (PMID 38164286, 2024). "Indeed, cancer cells that express high levels of pluripotency markers such as Sox2, Oct4 and Nanog have enhanced clone‐forming abilities." (PMID 39632282, 2024). "SOX2 is closely related to cancer stemness-related features." (PMID 38920983, 2024). "Altogether, SOX2 promotes the self-renewal and cancer cell stemness." (PMID 38331879, 2024). "Similarly, a previous study reported that combination treatment leads to increased chemosensitivity of cancer cells through the down-regulation of SOX-2." (PMID 38864530, 2024). "However, in the presence of carboplatin, there was a significant increase in SOX2 expression relative to carboplatin-treated cancer cells cultured alone." (PMID 39287565, 2024). "Additionally, the combination therapy substantially downregulated the expression of the stemness gene Sox2 and the cancer stem cell marker CD44, contrasting with the effects of single MRTX1133 treatment." (PMID 39297408, 2024). "However, the overexpression of SOX2 has been demonstrated in many different types of human cancers, and its expression promotes neoplastic progression by accelerating cancer cell proliferation, migration, invasion, and metastasis." (PMID 39272828, 2024). "Whether the SOX2-positive NC cells represent a cancer stem cell population is a critical question to be investigated in the future." (PMID 38724194, 2024). "In summary, because glycolysis and VM formation are prevalently dysregulated in cancers, therapeutic interventions based on the SOX2-lncRNA AC005392.2-GLUT1 axis may be promising in the treatment of CRC patients." (PMID 38044399, 2023). "We speculate that high SOX2 expression and low ISGs expression are utilized by cancer cells to ensure survival." (PMID 37058447, 2023). "YY1 is overexpressed in NSCLC and co-expressed in the NSCLC gene network, probably related with the activation of cell proliferation and invasion, forming a regulatory loop with cancer stem cell transcription factors (SOX2, OCT4, and BMI1) in the NF-kB/PI3K /AKT axis." (PMID 36661515, 2023). "The pathogenic role of SOX2 in AML is underexplored despite the observation that SOX2 may serve as an oncogene in some cancers." (PMID 37835401, 2023). "With hypoxia being a common feature of the microenvironment of solid tumors, it is worth mentioning that hypoxia and its master regulators—hypoxia-inducible factors (HIFs)—participate in stem-like maintenance in various cancers and dysregulate stemness genes such as SOX2." (PMID 37686684, 2023). "Finally, our validation of SOX2-enriched SEs showcased their contribution to target gene expression in both stem cells and cancer cells." (PMID 37930832, 2023). "SOX2 stands as a stemness gene, which modulated cancer initiating and drug-resistant behavior." (PMID 37310654, 2023). "In addition, inflammatory markers such as COX-2 are co-expressed with CSC markers including SOX-2 in cancer." (PMID 37259369, 2023). "Based on cancer stem cell hypotheses, not only coding transcripts such as Oct4, Nucleostemin, Sox2, and Klf4, but also long non-coding transcripts, contribute to regulating CSC proliferation." (PMID 37104007, 2023). "Moreover, PA treatment enhances the expression of stemness-related genes such as SOX2 leading to cancer stem cell properties of HepG2 cells." (PMID 37828054, 2023).
cancer (continued). "Moreover, MDA‐MB‐231 cells grown in FN‐silk networks had high cancer stem cell markers (i.e., NANOG, OCT4, and SOX2), accompanied by an up‐regulation of genes associated with basement membrane degradation and invasiveness (i.e., HIF1α, ITGAV, and MMP14)." (PMID 37693069, 2023). "In addition, we found that cancer stemness markers, such as SOX2, Nanog, CD44, CD133, and ALDH1 were significantly upregulated in xenograft tumors overexpressing SAMD9." (PMID 36757050, 2023). "The current study reported that SOR significantly inhibits DEN-induced lung early oncogenic events by decreasing the inflammatory parameters in the precancerous microenvironment and the level of SOX-2 protein, which mediates the self-renewal of cancer stem cells." (PMID 37259369, 2023). "Moreover, SOX2 has been recognized as a powerful oncogene in various cancer types, where it regulates cancer stem cells (CSCs) and functionally relates to several other hallmarks." (PMID 37042179, 2023). "Moreover, Sox2, Oct3/4, and Nanog are essential for the maintenance of cancer stem cell–like side population cells in MM." (PMID 36752202, 2023). "In addition, studies have emphasized the central roles of Wnt/β-catenin in maintenance of EMT and stemness, which is achieved by regulating SOX2 in cancer cells." (PMID 37147666, 2023). "Interestingly, latent competent cancer cells expressing SOX2/SOX9 increase dormant CSCs (or latency-competent cancer cells) that downregulate NKG2DL through a unique mechanism that produces the WNT inhibitor DKK1, thus evading NK cell-mediated immunity." (PMID 37394580, 2023). "Sox2 is also a cancer stem cell marker currently recognized by researchers." (PMID 36869031, 2023). "On the other hand, SOX2 promotes skin and lung cancer progression." (PMID 37738673, 2023). "Moreover, WAC-AS1 increases tumorsphere formation and the expression of SOX2, a master regulator of cancer stemness and CSC self-renewal, while decreasing the chemo-sensitivity of OS cells, indicating that WAC-AS1 regulates the stemness of OS." (PMID 37957698, 2023). "SOX2 overexpression occurs in multiple types of cancer (reviewed in 21,22)." (PMID 37738673, 2023). "Therefore, we propose that FOXA1 is one of the key players responsible for the reprogramming of the SRR124–134 cluster in cancer, which then drives SOX2 overexpression in breast and lung tumors." (PMID 37738673, 2023). "This could be explained by the highly complex and interconnected network in which SOX2 functions in stem and cancer cells." (PMID 37760529, 2023). "Cadherin may up-regulate Nanog and Sox2 to promote stemness in cancer cells, leading to chemoresistance." (PMID 37291676, 2023). "Moreover, transcriptional control of miR-34a by HOTAIR influenced SOX2 (SRY (sex determining region Y)-Box 2), an essential stemness factor regulating the self-renewal capacity of cancer stem cells." (PMID 37175800, 2023). "Aberrant expression of embryonic stem cell proteins such as Sox2, Oct4 and Myc has been shown in many cancer types, and the expression of these proteins in various cancer models has been found to significantly correlate with cancer stem-like (CSL) features and poor clinical outcomes." (PMID 38203669, 2023). "MSX2 interacts with SOX2 in oral SCC to control cancer stem cell-like traits." (PMID 38110859, 2023). "During such a reversion, cancer cells re-express several previously repressed genes, including those involved in cell plasticity (Oct4, SOX-2, and Nanog), while genes (PSEN1, Notch-1) and proteins (SNAI1, αSMA, N-cadherin) supporting epithelial–mesenchymal transition (EMT) are downregulated." (PMID 37511359, 2023). "SOX2 maintains cancer cell stem cell function by regulating the Hippo pathway." (PMID 37240338, 2023). "It interacts with Sox2 during the process of oncogenesis in cancer stem cells." (PMID 38110859, 2023).
cancer (continued). "To confirm the direct involvement of SOX2 in oncogenic and inflammatory activities, we performed pathway analysis on SOX2 ChIP-seq data and observed a strong enrichment in pathways driving several cancer entities as well as NFkB-related inflammatory properties (IL17 signaling pathway)." (PMID 36932385, 2023). "Cancer stem cells (CSCs) are a small subset of tumor cells with stem cell properties; one of the proposed criteria for their definition is expressing the transcription factors Nanog, Oct3/4, and Sox2." (PMID 37240338, 2023). "Also, the activation of core pluripotency transcription factor machinery, namely OCT4 (encoded by POU5F1), SOX2, Myc, or NANOG, is frequently observed in cancer stem cell-like tumor types and associated with worse patient survival." (PMID 36674511, 2023). "High expression of Sox2 is related to poor prognosis of cancer treatment." (PMID 37958844, 2023). "This fluorescent protein has been designed for thedetection of cancer stem cells.Figure 2Ashows that transduced A549 cells have a significant fluorescenceintensity in the red spectrum, which allows for the identification of the Oct4and Sox2 activities." (PMID 37153502, 2023). "In addition to MCF-7 cells, we found that H520 (LUSC), PC-9 (LUAD) and T47D (luminal A BRCA) cancer cell lines, which display varying levels of SOX2 expression, also gained substantial enhancer features at SRR124 and SRR134 when compared with normal tissue." (PMID 37738673, 2023). "The activation of STAT3 would also lead to various STAT3-dependent pathways, such as the interleukin-8/STAT3 (IL-8/STAT3) and EGFR/STAT3/SRY-box transcription factor 2 (EGFR/STAT3/SOX2) pathways, which have been shown to play important roles in cancer stemness." (PMID 37760799, 2023). "In addition, FOXO1, an upstream transcription factor of SOX2, participating in cancer stemness had been identified to participate in paclitaxel resistance in OC." (PMID 38143770, 2023). "NANOG homeobox (NANOG), sex determining region Y-box 2 (SOX2), and OCT4, common regulators of stemness, could mediate cancer proliferation and metastasis, which are associated with poor overall survival and advanced disease stage." (PMID 36830834, 2023). "Moreover, HIFs can regulate the expression of multipotency markers, such as Sox2 and Oct4, in cancer stem cells." (PMID 37016436, 2023). "SOX2 is a marker of cancer stem cells that is highly expression in response to radiotherapy." (PMID 37658588, 2023). "Surprisingly, the mRNA levels of PTBP1, together with three pluripotency factors Oct4, Nanog and Sox2 were robustly elevated in spheroid cultures than in monolayer cultures of two GC cells, which were responsible for converting cancer cells from differentiated to a stem-cell-like state." (PMID 36635500, 2023). "Moreover, dysregulation of SOX2 also functions as a critical factor contributing to cancer pathogenesis." (PMID 37147666, 2023). "To evaluate whether the 3D culture dimensionalityaffected the stemness of cancer cells, we examined the expressionlevels of the two stemness-related transcription factors: namely,Oct3/4 and SOX2." (PMID 35687666, 2022). "The last two subpopulations are regarded as the original cancer cells and the terminal cancer cells respectively, one with over-expressed stem-related genes SOX2 and ALDHA1 and the other with high expressions of genes enriched in steroid biosynthesis, mismatch repair and peroxisome pathways." (PMID 36397138, 2022). "These include ALDH1, ABCG2, CD44, CD133, NANOG, and SRY-box transcription factor 2 (SOX2), all of which have been linked to chemoresistance in a number of first line anti-cancer therapies—for example, axitinib is an oral, potent, small molecule ATP-competitive multitarget tyrosine kinase inhibitor." (PMID 36338714, 2022).
cancer (continued). "Importantly, when combined with the R-CHOP regimen, the PI3K/AKT inhibitor converted CSCs to differentiated cancer cells by destabilizing SOX2 level, thus inhibiting the growth of resistant cells that were highly sensitive to the R-CHOP regimen." (PMID 35309116, 2022). "Importantly, they found that Sestrin2 inhibits the Wnt/β-catenin pathway, thereby reducing cancer cells stemness through downregulation of sex-determining region Y-Box 2 (Sox2), octamer-binding transcription factor 4 (Oct4), Kruppel-like factor 4 and c-myc." (PMID 35527284, 2022). "We speculate that the genes needed to counterbalance the inhibitory effects of elevated SOX2 are likely to vary by cancer type." (PMID 35454854, 2022). "Moreover, there is evidence that SOX2 mediates resistance towards established cancer therapies, and it is thought to be over-expressed in CSCs, where is involved in the regulation of the stemness and self-renewal." (PMID 36566021, 2022). "EMT-like phenotypic transitions which transform differentiated cells to dedifferentiated cells with stem cell-like properties is related to increased expression of certain normal and cancer stem cell markers such as Slug, Twist, Sox2, CD44, Nanog, CD133 (PROM1), Oct4, and ABC membrane transporters." (PMID 36361653, 2022). "SOX2, UBTF, NFE2L2, TCF3 and STAT3 were underlined as common transcriptional factors, which are responsible for the upregulation of genes involved in processes of the epithelial–mesenchymal transition, cancer stemness, invasion and migration of GBM." (PMID 36231068, 2022). "Moreover, the cancer stem cell-related markers, Nanog, SOX2 and LIN28A, were induced by the depletion of LPAL2." (PMID 36010685, 2022). "As a crucial transcription factor, SOX2 can trigger drug resistance in cancer cells." (PMID 36247876, 2022). "The ability of HPV integration to alter expression of nearby human genes (within 500 Kb) has been demonstrated in both OPSCC and UCSCC with recurrent integration sites identified near genes implicated in cancer such as MYC, MYB, PVT1, RAD51B, EMBP1, CD274/PD-L1, and SOX2." (PMID 36139648, 2022). "It is, for example, highly expressed in pluripotent cells of the inner cell mass of the developing embryo, but SOX2 expression is also reported to be correlated with carcinogenesis, chemoresistance and maintenance of the stem cell-like phenotype in cancer cells." (PMID 35945296, 2022). "EMT is essential in cancer development and CSCs and Zeb1 have been implicated in the expression of several stem cell-associated transcription factors, including those with oncogenic potentials, such as BMI1, KLF4 and SOX2." (PMID 35404029, 2022). "SOX2, a stemness biomarker, is related to drug resistance in many cancers." (PMID 35059870, 2022). "In addition, SOX2 is highly expressed in premalignant lesions, such as squamous dysplasia and carcinoma in situ in the lung." (PMID 35945296, 2022). "Cancer-associated gene (CAGE), a cancer/testis antigen, could bind to SOX2 and regulate the cancer stem cell-like properties of breast cancer cells." (PMID 35682560, 2022). "ESC genes that are re-expressed in cancer include the core transcription factors (Sox2, Oct-4, and Nanog) that are necessary for pluripotency and cell survival as well as factors that regulate epithelial mesenchymal transition (EMT), the first step towards cancer cell migration and invasion." (PMID 35892887, 2022). "Some reports pertained to the role of SOX2 in cancer metabolism." (PMID 35629138, 2022). "Interestingly, it has been proposed that IR treatment induces stemness in cancer cells via the upregulation of SOX2, among other known stemness factors." (PMID 36497175, 2022).
cancer (continued). "A recent study using next-generation sequencing technology to test cancer-related genes has shown that several targeted mutations (KRAS, PIK3CA, IRS2, Sox2, and HRR genes) may potentially become effective targeted treatment sites for patients." (PMID 35909972, 2022). "SOX2 is mainly considered as a molecular marker of cancer stem cells." (PMID 36293387, 2022). "In addition, the expression of key genes involved in cancer differential therapy, Sox2, and Oct4 was analyzed." (PMID 36908807, 2022). "SOX2 expression and activity is dys-regulated in different cancer types." (PMID 36566021, 2022). "Interestingly, cancer stem cell marker Sox2 exhibited a robust reduction in transcription after DkkMo treatment under in vitro conditions." (PMID 35277659, 2022). "It indicated that EphrinB2 increased the population of cancer stem cells through Sox2 and Nanog." (PMID 36402751, 2022). "Therefore, silence METTL3 can reduce the expression of SOX2, which further enhance the sensitivity of cancer cells to γ-irradiation." (PMID 35022030, 2022). "The level of CD133 and SOX2 expression in GBM may be indicative of the presence of a treatment-resistant cancer cell subpopulation." (PMID 36333778, 2022). "Here we found AR expression in RCC cells decreased in response to hypoxia, which might then lead to increase the cancer stem cells (CSC) phenotype through the lncTCFL5-2-modulated YBX1/SOX2 signals." (PMID 36397101, 2022). "Moreover, resveratrol clearly inhibited epithelial-mesenchymal transition-induced self-renewal ability of glioma stem cells and inhibited EMT-induced cancer stem cell markers Sox2 and Bmi." (PMID 35566016, 2022). "The oncogenic mutation HRASV12 has been found to induce activity of CDK1 and enhance protein O-GlcNAcylation, both of them having essential roles in induction of SOX2 expression and cancer stem cell properties in fibroblasts and cancer cell lines harboring RAS mutations." (PMID 36266723, 2022). "Moreover, HOXB‐AS3 expression was positively correlated with the presence of cancer stemness markers, SOX2 and OCT4, in patients." (PMID 35253323, 2022). "Notably, several studies reported the ability of HIF1 to induce SOX2 in cancer cells, and HIF1 acted as an oxygen sensor in the present study." (PMID 35035654, 2022). "Together with previous work from our laboratory, the findings presented here demonstrate that elevating SOX2 in seven types of human cancer invariably leads to growth inhibition, strongly suggesting that this is a general effect of elevated SOX2 in human cancer." (PMID 35454854, 2022). "Additionally, the cancer stemness markers Oct-4, Nanog, and Sox2 increased approximately fivefold in each cell line (Nanog and Oct-4 data shown in supplemental)." (PMID 36284815, 2022). "Further, SOX2 may be involved in cancer stemness, as high SOX2 expression facilitates drug resistance." (PMID 35059870, 2022). "In addition to its essential role in stem cell self-renewal and reprogramming, Sox2 also plays a role in the survival of stem cells and cancer cells." (PMID 35227273, 2022). "The treatment of EphrinB2-Fc on A549 cells increased the ratio of CD133+ cancer stem cells and knockdown of Sox2 and Nanog by siRNA could reverse the enrichment of cancer stem cells induced by EphB1 trans signaling." (PMID 36402751, 2022). "Likewise, sCD146 upregulated the expression of the cancer stem cell markers nanog, oct4 and sox2 in U87 cells." (PMID 36274147, 2022). "Consequently, the cancer-promoting effect performed by SOX2 in HCC is likely to be mainly attributable to its ability to control the stemness of HCC cells." (PMID 35267473, 2022). "Indeed, stem-related transcription factors, including Oct-3/4, Sox2, Klf-4 and Nanog have been used to identify CSCs subpopulations in a variety of cancers, such colorectal cancer (CRC)." (PMID 35205738, 2022).